PSMD4 (proteasome 26S subunit ubiquitin receptor, non-ATPase 4)
Description:
Component of the 26S proteasome, a multiprotein complex involved in the ATP-dependent degradation of ubiquitinated proteins. This complex plays a key role in the maintenance of protein homeostasis by removing misfolded or damaged proteins, which could impair cellular functions, and by removing proteins whose functions are no longer required. Therefore, the proteasome participates in numerous cellular processes, including cell cycle progression, apoptosis, or DNA damage repair. PSMD4 acts as an ubiquitin receptor subunit through ubiquitin-interacting motifs and selects ubiquitin-conjugates for destruction. Displays a preferred selectivity for longer polyubiquitin chains.
Synonyms: AF; ASF; MCB1; S5A; AF-1; Rpn10; pUB-R5
Tractability: Small molecule: an approved drug acts on it; a structure with a bound ligand is known; a high-quality ligand is known. PROTAC: UniProt records ubiquitination sites on it; ubiquitination databases record sites on it; its protein half-life has been measured.
Gene: Protein-coding gene on chromosome 1 (151,254,709 to 151,267,479, forward strand). Ensembl gene ENSG00000159352.
Subcellular location (Human Protein Atlas): Nucleoplasm; Cytosol
Pathways (Reactome):
Metabolism of proteins: Proteasome assembly
Gene Ontology:
Molecular function: identical protein binding; molecular adaptor activity; protein binding; RNA binding
Biological process: cellular response to type I interferon; proteasomal protein catabolic process; proteasome-mediated ubiquitin-dependent protein catabolic process; regulation of proteasomal protein catabolic process; response to oxidative stress
Cellular component: proteasome complex; cytosol; nucleus; proteasome accessory complex; synaptic vesicle
Genetic constraint (gnomAD): Loss-of-function variants: 5 observed, 35.59 expected, observed/expected ratio (o/e) 0.14, 90% interval 0.072 to 0.29. The upper end of that interval is the gene's LOEUF score, 0.29, which puts it in group 1 of 6, group 1 being the genes least tolerant of losing a copy. Missense variants: 269 observed, 472.56 expected, observed/expected ratio (o/e) 0.57, 90% interval 0.51 to 0.63. Synonymous variants: 140 observed, 168.2 expected, observed/expected ratio (o/e) 0.83, 90% interval 0.73 to 0.96.
Homologues: Orthologues: macaque PSMD4 (100% identical), pig PSMD4 (99% identical), guinea pig PSMD4 (99% identical), rabbit PSMD4 (99% identical), rat Psmd4 (99% identical), chimpanzee PSMD4 (97% identical), mouse Psmd4 (96% identical), tropical clawed frog psmd4 (89% identical), zebrafish psmd4a (86% identical), zebrafish psmd4b (81% identical), Drosophila melanogaster Rpn10 (63% identical), Caenorhabditis elegans rpn-10 (46% identical).
Diseases named in the same sentence as PSMD4 in open-access papers:
PSMD4 is named in the same sentence as 34 diseases in open-access papers, as found by Europe PMC text mining. Sharing a sentence is not in itself a finding about the gene and the disease. The quoted sentences say what the papers report.
colorectal cancer (6 papers, 2017 to 2023). A primary or metastatic malignant neoplasm that affects the colon or rectum. "Antioxidant response element-bound nuclear Nrf2 (nNrf2) promotes chemoresistance in colorectal cancer through the EMT pathway via the NF-κB/AKT/β-catenin/ZEB1 cascade by inducing PSMD4 expression." (PMID 37349676, 2023). "(2021) showed that PSMD4 is a potential target in mouse colorectal cancer, mediating the enhancement of immunoproteasome activity by atractylenolide I (ATT-I), making the body more responsive to immune checkpoint blocking therapy." (PMID 35782126, 2022). "Increased expression of cNrf2 via the reciprocal talk between cNrf2 and PSMD4 (proteasome 26S subunit, non-ATPase 4) promoted colorectal cancer with more aggressive tumors in in vitro and in vivo models." (PMID 31013812, 2019). "These experimental observations were confirmed in colorectal cancer patients, in whom a higher prevalence of unfavorable chemotherapeutic response was noted in subjects with cNrf2- and PSMD4-positive tumors." (PMID 31434263, 2019). "Recent research further suggested the role of PSMD4 in colorectal cancer chemoresistance via the cNrf2-mediated signaling cascade." (PMID 31013812, 2019). "A higher prevalence of unfavorable chemotherapeutic response in colorectal cancer patients with cNrf2, PSMD4-positive, p-p65-positive, and nuclear β-catenin tumors was observed when compared to their counterparts." (PMID 29899863, 2018). "PSMD4 may represent a useful molecular target for overcoming cNrf2-mediated 5-FU resistance in colorectal cancer." (PMID 29899863, 2018). "We therefore hypothesized that cNrf2-induced PSMD4 expression may promote more than just colorectal cancer tumor aggressiveness and may also confer chemoresistance, consequently resulting in patients with poor outcomes." (PMID 29899863, 2018). "Our findings presented here provide evidence that carfilzomib may overcome the 5-FU resistance in colorectal cancer induced by the NF-κB/β-catenin/ZEB1 activation that is mediated by cNrf2-induced PSMD4 expression." (PMID 29899863, 2018). "Therefore, the chemoresistance mediated by cNrf2-induced PSMD4 expression in colorectal cancer may occur predominately through the epithelial-to-mesenchymal transition (EMT)." (PMID 29899863, 2018). "In colorectal cancer, cytoplasmic NRF2 expression has been reported to promote cancer cell invasion via regulation of PSMD4, and a higher frequency of cytoplasmic NRF2 in HER-2-positive cancers and brain metastases might reflect greater invasiveness and aggressiveness." (PMID 28260828, 2017).
colon carcinoma (5 papers, 2018 to 2025). "PSMD4 overexpression has been observed in colon carcinoma, hepatocellular carcinoma, and breast cancer." (PMID 33110365, 2020). "In colon cancer cells, increased cNrf2 (nuclear factor-like 2) expression promotes colorectal cancer with more aggressive tumors via upregulating PSMD4." (PMID 33110365, 2020). "Consistent with the present study, increased proteasomal subunit S5a (PSMD4) protein expression and proteasomal activity in colon cancer were related to an enhanced activation of Nrf2." (PMID 29899863, 2018). "This hypothesis is supported by our observation that in human colonic cancer cells, PSMD4 deletion results in a significantly higher proportion of cells in the G1 phase under control conditions (DMSO)." (PMID 39918307, 2025). "In addition, the expression of PSMD4 is abnormal in tumors such as colon cancer, liver cancer, breast cancer, and esophageal cancer." (PMID 36518627, 2022). "An overexpression of PSMD4 has been found in human colon cancer." (PMID 33110365, 2020). "PSMD4 has been found to be overexpressed in specimens of human colon cancer." (PMID 33110365, 2020). "In addition, cNrf2 is a stronger promoter than nNrf2 for colony formation, soft agar growth, and invasiveness of colon cancer cells because it increases PSMD4 expression." (PMID 29899863, 2018). "Mechanistic studies demonstrated that Nrf2-mediated PSMD4 expression may promote more than just colony formation, cell invasion, and soft agar growth, and may also confer 5-FU resistance in colon cancer cells via the NF-κB/AKT/β-catenin/ZEB1 cascade." (PMID 29899863, 2018).
breast carcinoma (4 papers, 2013 to 2023). "Studies have shown that the prognostic model genes TK1, LOX, KDM5B, PSMD4, and NFE2L3 are associated with breast cancer progression, prognosis stratification, and clinical drug resistance." (PMID 37767092, 2023). "Furthermore, PSMD4 has been amplified and overexpressed in breast cancer, and this overexpression is correlated with low survival rates." (PMID 33110365, 2020). "However, previous studies have also shown that nuclear factor kappa B (NF-κB) and PSMD4 inhibited breast cancer proliferation via epidermal activation growth factor receptors." (PMID 33110365, 2020). "PSMD4 is overexpressed and amplified in breast cancer, correlating with poor survival rates." (PMID 33110365, 2020). "Thymidine kinase-1 (TK1), lysyl oxidase (LOX), lysine demethylase 5B (KDM5B), proteasome 26S subunit non-ATPase 4 (PSMD4), and nuclear factor erythroid 2-like 3 (NFE2L3) genes are implicated in relapse and poor prognosis of patients with breast cancer." (PMID 37767092, 2023).
hepatocellular carcinoma (4 papers, 2020 to 2024). A malignant tumor that arises from hepatocytes. "PSMD4 increases cell proliferation via regulation of the PTEN/Akt pathways in hepatocellular carcinoma (HCC) cells; in addition, a significant correlation has been found between HIF1a expression and PSMD4 expression in HCC patients." (PMID 33110365, 2020).
pancreatic cancer (4 papers, 2018 to 2025). "Inhibition of the Nrf2 transcription factor by the alkaloid trigonelline renders pancreatic cancer cells more susceptible to apoptosis through decreases in PSMD4 expression and proteasomal activity." (PMID 29899863, 2018). "Systematic evaluation of PSMD1-14 expression revealed significant upregulation (p<0.05) of PSMD1, PSMD2, PSMD3, PSMD4, PSMD7-PSMD14 transcripts in pancreatic tumor tissues compared with adjacent normal controls, with the notable exception of PSMD6 which demonstrated reduced mRNA expression." (PMID 40182048, 2025).
esophageal cancer (3 papers, 2022 to 2023). A primary or metastatic malignant neoplasm involving the esophagus. "PSMD4 was shown to affect esophageal cancer by inhibiting endoplasmic reticulum stress and degree of cellular malignancy." (PMID 37349676, 2023).
prostate carcinoma (3 papers, 2020 to 2021). A carcinoma that arises from epithelial cells of the prostate gland. "Upregulation of the PSMD4 gene by hypoxic conditions in prostate cancer cells suggests a novel therapy for treatment." (PMID 34839279, 2021). "The purpose of the present study is to identify the hypoxic regulation of the PSMD4 gene in a prostate cancer model." (PMID 33110365, 2020). "In this work, we elucidated the effect of hypoxia on PSMD4 gene expression in prostate cancer cells (PC3)." (PMID 33110365, 2020). "Our findings show hypoxia-regulated PSMD4 expression in prostate cancer and give valuable information for designing novel treatments." (PMID 33110365, 2020). "The study delivers new data on PSMD4 regulation by HIF1a in the prostate cancer cell line." (PMID 33110365, 2020). "The data suggest that PSMD4 could be a novel hypoxia target gene for prostate cancer therapy." (PMID 33110365, 2020). "There are virtually no studies available on the hypoxic regulation of the PSMD4 gene in a prostate cancer model." (PMID 33110365, 2020).
myeloma (2 papers, 2019 to 2020). "When our kinetic Ix-response profiles in HMCLs and patients were compared with Shaughnessy’s GEP80-postBz, 10 genes (primarily involved in PUP) were found similar between all the subgroups, including PSMD4—the novel high-risk gene in myeloma patients." (PMID 32724061, 2020).
ovarian carcinoma (2 papers, 2016 to 2022). A malignant neoplasm originating from the surface ovarian epithelium. "Intriguingly, amplification of PSMB3, PSMB4, and PSMD4 have also been observed in breast- and ovarian cancer." (PMID 36123629, 2022).
breast tumor (1 paper, 2021). "Immunohistochemical (IHC) images revealed dense distributions of PSMD2 and PSMD4, while the other PSMDs, including PSMD1, PSMD2, PSMD3, PSMD7, PSMD12, and PSMD14, were moderately distributed in breast tumor samples." (PMID 34839279, 2021).
colorectal tumor (1 paper, 2025). "Proteome-wide TPP-TR of colorectal tumor cells identified the proteasome 26S subunit non-ATPase 4 (PSMD4) as a key target of atractylenolide I. Binding to PSMD4 enhanced immunoproteasome activity, increased antigen presentation, and improved the immune response to cancer cells." (PMID 40362180, 2025).
graft versus host disease (1 paper, 2024). An immune system disorder that occurs after allogeneic hematopoietic stem cell transplant and is a reaction of donor immune cells against host tissues. "The pathway enrichment analysis identified six VDM-associated pathways (type 1 diabetes, graft-versus-host disease, allograft rejection, antigen processing and presentation, viral myocarditis, and targets of PSMD4 regulation) which were all interrelated within the framework of immunity." (PMID 38245754, 2024).
Hypercholesterolemia (1 paper, 2022). An increased concentration of cholesterol in the blood. "PSMD4 encodes proteasome 26S subunit ubiquitin receptor, which is a proteasome-related gene that is significantly downregulated in hypercholesterolemia." (PMID 35480309, 2022).
ovarian serous carcinoma (1 paper, 2023). "Among them, up-regulation of PSMD4, PSMD8, and PSMD14 mRNA expression was significantly associated with poor OS in patients with ovarian serous carcinomas." (PMID 37349676, 2023). "Up-regulation of PSMD4/8/14 mRNA expression was associated with poor OS, and the up-regulation of PSMD2/3/5/8 mRNA expression was associated with poor PFS in patients with ovarian serous carcinomas." (PMID 37349676, 2023).
Sepsis (1 paper, 2022). Sepsis is defined as life-threatening organ dysfunction caused by a dysregulated host response to infection. "The GSE171546 dataset has a total of 20 samples, and we used five normal myocardial tissue data and five CLP-induced sepsis mouse model myocardial tissue data to verify the expression of PSMD4." (PMID 35782126, 2022).
urothelial bladder carcinoma (1 paper, 2023). "In urothelial bladder carcinoma, PSMD2, PSMD3, PSMD4, PSMD8, and PSMD11 genes are overexpressed." (PMID 36934426, 2023).
cancer (16 papers, 2014 to 2025). A tumor composed of atypical neoplastic, often pleomorphic cells that invade other tissues. "However, the other subunits of proteasome, such as PSMD3, PSMC2, and PSMD4, were upregulated in several cancers and associated with prognosis." (PMID 34239933, 2021). "Three of these four genes, BRCA1, PSMD4, and RPL3, are reported as cancer genes, and STAT1 is associated with both cancer and AIDs." (PMID 40429780, 2025). "Future research is needed to determine how PSMD4 expression varies within colonic epithelial cells or cancer cells, and whether these differences impact cellular responses to colibactin or its carcinogenic potential in vivo." (PMID 39918307, 2025). "For what concerns the in vivo tumor expression of proteasome subunits and ubiquitin, it is first worth underscoring that the immunostaining of two constitutive structural subunits, such as PSMA4 and PSMD4, was very faint in cancer cells of DMSO-treated animals." (PMID 34561494, 2021). "In addition, this correlation analysis revealed cancer-specific addiction associated with coordinated upregulation of another subset of genes that reside in the same region of chromosome 1 and are involved in vesicle and protein trafficking (GBA, GPR89A, NCSTN, PSMD4, VPS45)." (PMID 29535384, 2018). "Cancer cells treated with proteasome inhibitors also upregulate autophagy and knockdown of two proteasomal ubiquitin receptors, PSMD4/S5a and ADRM1, in HeLa cells promotes compensatory SQSTM1/p62-mediated autophagy that clears accumulated polyubiquitinated substrates." (PMID 32887506, 2020). "In conclusion, the comprehensive pan-cancer analysis presented here demonstrated that several PSM genes (e.g. PSMA1, PSMB4-5, PSMB8-10, PSMD2, PSMD4, PSMD11, PSME1-3, and PSMG3) may be putative biomarkers for determining prognosis and choice of treatment for different cancer types." (PMID 36123629, 2022). "Furthermore, co-amplification of PSM genes located in close proximity to one another (e.g. PSMB5 and PSMB11, 14q11.2; PSMB4 and PSMD4, 1q21.3; PSMB8 and PSMB9, 6p21.32) or known cancer drivers (e.g. co-amplification of ERBB2 and PSMB3) were also frequently amplified together." (PMID 36123629, 2022).
tumor (12 papers, 2014 to 2025). "Our previous study showed that Rpn10/PSMD4 (a 19S regulator) promotes tumor progression by regulating hypoxia-inducible factor 1alpha through the PTEN/Akt signaling pathway in HCC." (PMID 38745188, 2024). "A previous study indicated that the DUB PSMD4 promotes tumor growth and chemoresistance by stabilizing the ALK2 receptor during the initiation of the BMP6 signaling pathway." (PMID 33846536, 2021). "At present, there are several studies showed that PSMD4 could affected the development of most tumor disease." (PMID 35782126, 2022). "Numerous studies have found that PSMD4 plays a significant part in tumor progression." (PMID 33110365, 2020). "Numerous studies have shown that PSMD4 plays a significant part in tumor progression." (PMID 33110365, 2020). "In fact several genes such as CKS1B, PSMD4, IL6R, MCL1 involved in proliferation and survival of tumour cells, mechanisms of chemo refractoriness, and alteration of the microenvironment are located in the 1q21 region." (PMID 36755858, 2022). "Therefore, depending on the type of tumor, PSMD4 could have different roles." (PMID 33110365, 2020). "We observed higher expression of PSMD4 and PSMB4 protein levels in the recurrent tumors compared with the primary tumor and normal brain tissues." (PMID 32235770, 2020). "In addition, tumor vessels density and expression of some proteasome structural subunits (PSMA4, PSMD4, PSME1) and ubiquitin were evaluated." (PMID 34561494, 2021).
bacterial infections (1 paper, 2025). "Moreover, this work suggests that patients with dysregulated PSMD4 expression or other genes identified in our CRISPR/Cas9 screen that play essential roles in transcription and translation may be more susceptible to CRC, resulting from pks+ bacterial infections." (PMID 39918307, 2025).
myopathies (1 paper, 2023). "For example, MYL1, MYOM2, TRIM63 and PSMD4 have been broadly associated with myopathies but not directly to LVNC or DCM yet, and could therefore be considered as potential targets to investigate." (PMID 37644440, 2023).
PSMD4 also shares sentences with these, for which no sentence is quoted: infection (2 papers); liver cancer (2); neurological disease (2); Bardet-Biedl syndrome (1); Brain atrophy (1); chronic myelogenous leukemia (1); Epstein-Barr virus infection (1); Infertility (1); myelodysplastic syndrome (1); reproductive diseases (1); serous ovarian cancer (1); squamous cell carcinoma (1); type 1 diabetes (1); viral myocarditis (1).